HSD17B1 (hydroxysteroid 17-beta dehydrogenase 1)
Description:
Favors the reduction of estrogens and androgens. Converts estrone (E1) to a more potent estrogen, 17beta-estradiol (E2). Also has 20-alpha-HSD activity. Uses preferentially NADH.
Synonyms: 20-alpha-HSD; EDH17B2; EDHB17; SDR28C1; HSD17; MGC138140; 17-beta-HSD; E2DH
Tractability: Small molecule: a structure with a bound ligand is known; a high-quality ligand is known; it has a high-quality binding pocket; it belongs to a druggable protein family. PROTAC: a small molecule that binds it is known.
Target class: Enzyme; Oxidoreductase
Chemical probes: CHEMBL1650645, CHEMBL2041378, PD080833, PD082863, PD084457
Gene: Protein-coding gene on chromosome 17 (42,552,922 to 42,555,214, forward strand). Ensembl gene ENSG00000108786.
Subcellular location: Cytoplasm
Subcellular location (Human Protein Atlas): Cytosol
Pathways (Reactome):
Metabolism: Estrogen biosynthesis
Sensory Perception: The canonical retinoid cycle in rods (twilight vision)
Gene Ontology:
Molecular function: estradiol 17-beta-dehydrogenase [NAD(P)+] activity; estradiol binding; NADP binding; NADP+ binding; protein binding; protein homodimerization activity; small molecule binding; steroid binding; 17-beta-hydroxysteroid dehydrogenase (NADP+) activity; testosterone dehydrogenase (NADP+) activity; testosterone dehydrogenase (NAD+) activity
Biological process: estrogen biosynthetic process; testosterone biosynthetic process; bone development; cellular response to metal ion; steroid biosynthetic process
Cellular component: cytosol; cytoplasm
Genetic constraint (gnomAD): Loss-of-function variants: 16 observed, 22.18 expected, observed/expected ratio (o/e) 0.72, 90% interval 0.49 to 1.1. The upper end of that interval is the gene's LOEUF score, 1.1, which puts it in group 4 of 6, group 1 being the genes least tolerant of losing a copy. Missense variants: 533 observed, 458.68 expected, observed/expected ratio (o/e) 1.16, 90% interval 1.08 to 1.25. Synonymous variants: 243 observed, 210.58 expected, observed/expected ratio (o/e) 1.15, 90% interval 1.04 to 1.28.
Homologues: Orthologues: chimpanzee HSD17B1 (99% identical), macaque HSD17B1 (76% identical), dog HSD17B1 (73% identical), guinea pig HSD17B1 (70% identical), pig HSD17B1 (68% identical), rat Hsd17b1 (68% identical), mouse Hsd17b1 (67% identical), tropical clawed frog hsd17b1 (47% identical), zebrafish hsd17b1 (45% identical). Paralogues in human: RDH16 (25% identical), RDH5 (25% identical), SDR9C7 (24% identical), HSD11B2 (23% identical), HSD17B6 (23% identical), BDH1 (22% identical), DHRS9 (22% identical), HSD17B4 (21% identical), HSD17B7 (20% identical), HSD17B2 (19% identical), SDR16C5 (19% identical), HSD17B10 (18% identical), and 13 more.
Diseases named in the same sentence as HSD17B1 in open-access papers:
HSD17B1 is named in the same sentence as 50 diseases in open-access papers, as found by Europe PMC text mining. Sharing a sentence is not in itself a finding about the gene and the disease. The quoted sentences say what the papers report.
breast carcinoma (22 papers, 2010 to 2025). "Further, in ERα-positive pre-menopausal breast cancer patients who received tamoxifen treatment, low HSD17B1 expression was associated with reduced risk of recurrence." (PMID 28430630, 2017). "The development of breast cancer in humans, for instance, seems to be depending on the number of high-risk alleles present in CYP17 and HSD17B1." (PMID 31980012, 2020). "HSD17B1 and CYP17 gene polymorphisms were associated with breast cancer risk; hence HSD17B1 and CYP17 represented possible drug targets for breast cancer treatment." (PMID 29662904, 2018). "Collectively, these findings indicate that ERα-dependent estradiol signaling in breast cancer cell lines results in a reduction in HSD17B1, with a possible time-dependent effect on HSD17B2." (PMID 28977936, 2017). "The miRNAs control of the expression of HSD17B1 or HSD17B2 in breast cancer cells was examined using 50 miRNAs selected as described in the methods section." (PMID 28977936, 2017). "Several authors have proposed the use of HSD17B1 inhibitors for breast cancer, either as a single treatment, conceivably once resistance to aromatase inhibitors has arisen, or in combination with other treatments." (PMID 28430630, 2017). "In vitro, and in vivo studies using cell lines in rats and mice, as well as clinical studies have shown that the preferential reaction is reductive, and HSD17B1 expression has been found to be increased in breast cancer compared with unchanged tissue." (PMID 28430630, 2017). "Recently the progestin Dienogest was shown to down-regulate both HSD17B1 and aromatase expression in endometriosis patients, if this is also applicable in breast cancer remains to be seen." (PMID 28430630, 2017). "In postmenopausal ERα-positive breast cancer patients, the HSD17B1 expression was shown to be increased following steroidal aromatase inhibitor exemestane treatment." (PMID 28430630, 2017). "When analyzing copy number variation of the HSD17B1 gene it was shown that increased copy number was correlated with decreased breast cancer survival." (PMID 28430630, 2017). "As of the writing of this review, no publications experimentally examining the role of miRNAs in regard to HSD17B1 and 2 in breast cancer has been published." (PMID 28430630, 2017). "A similar study was conducted where inhibition of HSD17B1 activity prevented the proliferation of breast cancer cells in vitro, and reduced tumor volume and E2 plasma concentration in human breast cancer cell lines grown in vivo using mice and rat models." (PMID 28430630, 2017). "In conclusion, we show that estradiol negatively regulates HSD17B1 in breast cancer cell lines, and a possible time sensitive modulator of HSD17B2." (PMID 28977936, 2017). "RNA interference technique was used to knock down the 17β-HSD1 gene (HSD17B1) in the hormone-dependent breast cancer cell line T47D in steroid-deprived medium." (PMID 27900352, 2016). "Besides their role in breast cancer, which is relatively well-documented, HSD17B1 and HSD17B2 are also involved in several other forms of cancer." (PMID 28430630, 2017). "Those SNPs located in ERα, ERβ, HSD17B1, COMT and CYP1B1 genes may also be associated to mammographic density (MD), which is a strong and independent risk factor for breast cancer." (PMID 21092186, 2010). "More recently, studies using breast cancer cells where HSD17B1 was downregulated also show a significant reduction in proliferation and lowered E2 concentrations, and accompanied by increased DHT levels, likely as a result of the loss of E1 to E2 and DHT to 3α/3β-diol conversion by HSD17B1." (PMID 28430630, 2017). "On the contrary, increased expression of E2 HSD17B-synthetizing enzymes HSD17B1, HSD17B7 and HSD17B5 correlates with better ER+ breast cancer patient outcome for RFS and/or DMFS." (PMID 36674737, 2023). "These HSD17B1 and HSD17B2 isoforms were amplified at ~1.4% and ~0.6% in breast cancer, respectively." (PMID 31060224, 2019).
breast carcinoma (continued). "Taken together, these findings are the first to characterize miRNAs controlling HSD17B1 and HSD17B2 in breast cancer cell lines." (PMID 28977936, 2017). "We found eight miRNAs which modulate HSD17B1 or HSD17B2 expression, and five genes which appear able to control HSD17B1 or HSD17B2 expression in breast cancer cell lines." (PMID 28977936, 2017). "To date, no study has been published examining the role of miRNAs regarding HSD17B1 and HSD17B2 in breast cancer." (PMID 28977936, 2017). "Here we demonstrate that estradiol alters the expression of HSD17B1 and HSD17B2, two of the enzymes responsible for mediating the activity of estradiol in breast cancer cell lines." (PMID 28977936, 2017). "We aimed to investigate if estrogen and androgen-mediated signaling can influence the expression of HSD17B1 and HSD17B2 in breast cancer cell lines." (PMID 28977936, 2017). "While this review focused on the roles of HSD17B1 and HSD17B2, in breast cancer, this section will briefly describe other family members of note, with a focus on their role in breast cancer." (PMID 28430630, 2017). "Seven over-expressed breast cancer genes, namely BCAR1, HSD17B1, MMP14, PLAU, SFRP2, SPP1 and VCAN, had increased promoter methylation and their promoters contained the tumor-specific hypermethylated A-6 or A-7 HMRs." (PMID 25706888, 2015). "Furthermore, we aimed to identify microRNAs responsible for the regulation of HSD17B1 and HSD17B2 and to identify genes which control the expression of HSD17B1 and HSD17B2 in breast cancer cell lines." (PMID 28977936, 2017). "HSD17B1 has been shown to be under the regulation of microRNAs 210 and 518c in placental cells and microRNAs-10b, 145, 342, 17, 26a and 106b have been predicted to interact with HSD17B1 and HSD17B2 in breast cancer." (PMID 28430630, 2017). "Previously there have been studies where estradiol has been shown to mediate changes in HSD17B1 expression in lymphocytes, but to our knowledge, no such findings have been presented in breast cancer cell lines." (PMID 28977936, 2017). "We show that HSD17B1 and HSD17B2 are controlled by estradiol, dihydrotestosterone, and miRNAs, as well as modulated by several breast cancer-related genes, which could have future clinical applications." (PMID 28977936, 2017). "Taken together, estradiol mediates negative feedback control of HSD17B1 in ERα-positive breast cancer cell lines, which could be an important mechanism of how local estradiol concentrations are controlled." (PMID 28977936, 2017). "Therefore, HSD17B1 may not be an effective target in E1S-dependent, ER-positive, AI-resistant breast cancer treatment." (PMID 27228187, 2016). "Not much is known about the control of the expression of HSD17B1 and HSD17B2 in breast cancer, apart from that they are correlated with ERα expression, and that dihydrotestosterone can induce HSD17B2 expression in an AR-dependent manner in the breast cancer cell line T-47D." (PMID 28977936, 2017).
endometriosis (12 papers, 2010 to 2025). The growth of functional endometrial tissue in anatomic sites outside the uterine body. "The role of HSD17B1 937 A>G (rs605059) single nucleotide polymorphism (SNP) in development of endometriosis is still disputable." (PMID 28405865, 2017). "It has been suggested that genetic variants of HSD17B1, specifically the 937 A>G (rs605059) single nucleotide polymorphism (SNP), may contribute to endometriosis." (PMID 28405865, 2017). "Different preclinical studies have shown that HSD17B1 is involved in local estrogen production in the endometrium and endometrial diseases, including endometriosis." (PMID 35563206, 2022). "Gene expression ratio among CYP19A1, STS, and HSD17B1 in biopsies from endometriotic lesions and from eutopic endometrium of non-endometriosis patients (control)." (PMID 35591944, 2022). "The enzymes STS and HSD17B1 have been considered important in the pathogenesis of endometriosis, as indicated by the use of their inhibitors in the treatment of endometriosis." (PMID 35591944, 2022). "The gene encoding ARO, CYP19A1, was detected in all endometriosis tissue at levels all greater than found in control; STS and HSD17B1 presented consistently higher mRNA expression levels in DIE." (PMID 35591944, 2022). "In addition, the level of estrogen in endometriosis is abnormally high, and the enzymes related to estrogen synthesis, such as aromatase and HSD17β1 (Hydroxysteroid 17-Beta Dehydrogenase 1), are also highly expressed or increased in endometriosis lesions." (PMID 38397379, 2024). "The different effect of HSD17B1 937 A>G on the development of endometriosis in distinct ethnicities may have also resulted from genetic heterogeneity, size of the studied groups, and different populations’ exposure to environmental factors." (PMID 28405865, 2017). "A recent meta-analysis confirms lack of HSD17B1 rs605059 polymorphism association with endometriosis in the overall population as well as in subgroup ethnicities." (PMID 28405865, 2017). "Inhibitors of HSD17B1 are considered in treatment of endometriosis." (PMID 28405865, 2017). "Polymorphisms or haplotypes in HSD17B1 have been associated with increased risk for estrogen receptor-negative breast cancer, endometriosis, and endometrial cancer, but these associations have been modest and inconsistent." (PMID 22474448, 2012). "On the other hand, the lack of difference between gene and protein expression for the ratio HSD17B1:STS, in different endometriosis sites indicates that these enzymes are more closely regulated, as they show less expression variation." (PMID 35591944, 2022). "Our results did not identify endometriosis-specific amino acid changes in HSD17B1 but detected endometriosis preferential structural changes of HSD17B3, CYP19, and FSHR." (PMID 23139742, 2012). "Our data show that the relative expression of ARO, STS, and HSD17B1 vary in endometriotic tissue obtained from deep infiltrating lesions (DIE), superficial (SUP), ovarian (OMA), and eutopic endometrium from endometriosis patients (EE) lend support to the hypothesis." (PMID 35591944, 2022).
endometrial cancer (7 papers, 2012 to 2025). Primary or metastatic malignant neoplasm involving the endometrium (mucous membrane that lines the endometrial cavity). "CDKN2A was associated with several cancer-related pathways, including colorectal cancer, endometrial cancer, and pancreatic cancer, while HSD17B1 was enriched in metabolic and signaling pathways, such as galactose metabolism and MAPK signaling." (PMID 41226409, 2025). "Although the mRNA and protein levels of HSD17B1 are very low, this approach might be interesting for treatment of endometrial cancer, as recent reports have shown correlations between increased HSD17B1 mRNA levels and poor prognosis." (PMID 28674494, 2017).
preeclampsia (6 papers, 2018 to 2025). Preeclampsia is a hypertensive disorder of pregnancy that is characterized by new-onset hypertension with proteinuria presenting after 20 weeks of gestation, and depending on mild or severe forms may initially present with severe headache, visual disturbances, and hyperreflexia. "Some of the identified differently expressed genes include genes related to steroid metabolism, such as the cholesterol monooxygenase (CYP11A1) or hydroxysteroid 17β–dehydrogenase 1 (HSD17B1), highlighting the importance of steroid metabolism in preeclampsia." (PMID 39684415, 2024). "Predominantly placenta-expressed genes, down-regulated in module M1, are regulators of fetal growth (CSH1, HSD11B2), metabolism (ESRRG), estrogen synthesis (HSD17B1), and immune functions (LGALS14), some of which were reported to be down-regulated in preeclampsia." (PMID 30135684, 2018). "Previous studies have shown that ERRγ and HSD17B1 can regulate hormone synthesis, energy metabolism, and other processes, playing an important role in trophoblast differentiation and placental development, and their expression was decreased in FGR and preeclampsia." (PMID 39199376, 2024). "Notably, several HPGs associated with invasive EVTs (ADAM12, PAPPA2, PGF), and pregnancy complications such as preterm birth and preeclampsia (ADAM12, HSD17B1, KISS1, LGALS13, PAPPA2, SIGLEC6, ERVW-1), were found to be upregulated in human compared to rhesus placenta." (PMID 34154587, 2021).
colorectal cancer (4 papers, 2011 to 2025). A primary or metastatic malignant neoplasm that affects the colon or rectum. "In contrast, HSD17B1 expression is decreased in colorectal cancer through methylation of the promoter region, resulting in tumor progression via E2 reduction." (PMID 36830409, 2023). "HSD17B1 expression was analyzed in colorectal cancer cell lines (HT29, SW707) and primary colonic adenocarcinoma tissues collected from fifty two patients who underwent radical colon surgical resection." (PMID 22176788, 2011). "We observed little support for an association of gene variants in hormone receptors (ESR1, ESR2, PGR) and active estrogen synthesizers (HSD17B1, HSD17B2, and HSD17B4) with colorectal cancer risk among postmenopausal women of European descent." (PMID 21627810, 2011). "We found a significant decrease in HSD17B1 transcript (p = 0.0016) and protein (p = 0.0028) levels in colorectal cancer (CRC) from the proximal but not distal colon and rectum." (PMID 22176788, 2011).
prostate carcinoma (4 papers, 2015 to 2023). A carcinoma that arises from epithelial cells of the prostate gland. "Overview of the trials registered in the database Clinical Trials (ClinicalTrails.gov) for the use of aromatase, STS and HSD17B1 inhibitors in breast, endometrial, ovarian, prostate cancers and endometriosis." (PMID 37188267, 2023). "Furthermore, treatment with inhibitors of 5alpha-reductase type I and type II in prostate cancer cell lines resulted in increased HSD17B1, suggesting a role of DHT in up-regulating HSD17B1 expression in prostate cancer cells." (PMID 28430630, 2017). "No expression of HSD17B1 has been reported in prostate cancer, and the primary reductive HSD17B in prostate cancer is HSD17B5." (PMID 28430630, 2017). "We identified the β-hydroxysteroid-dehydrogenases HSD17B1 and HSD17B3 to be significantly up-regulated in metastatic compared to non-metastatic prostate cancer; they also correlated with the intensity of SR-BI expression." (PMID 26251134, 2015).
breast tumors (3 papers, 2017 to 2025). "Given the fact that both the expression and activity of HSD17B1 are significantly higher in the growth of breast tumors, it can be speculated that E2 may support dynamic growth of the CLs during early pregnancy." (PMID 33915762, 2021).
non-small cell lung carcinoma (3 papers, 2017 to 2024). A group of at least three distinct histological types of lung cancer, including non-small cell squamous cell carcinoma, adenocarcinoma, and large cell carcinoma. "In non-small cell lung cancer (NSCLC) the expression of HSD17B1 is increased as compared with healthy tissue." (PMID 28430630, 2017). "Furthermore, the presence of HSD17B1 has been confirmed in non-small cell lung cancer cell lines that facilitates the conversion of E1 to E2, suggesting that this gene acts as a mediator in this conversion process." (PMID 38850011, 2024). "In non-small cell lung cancer, increased HSD17B1 expression facilitates cancer progression." (PMID 39075554, 2024).
bladder cancer (2 papers, 2023 to 2024). "Notably, we found that suppressing HSD17B1 gene expression inhibited the invasion of bladder cancer cells." (PMID 39075554, 2024). "Additionally, cellular experiments underscore the pivotal role of HSD17B1 in bladder cancer metastasis and invasion, suggesting its potential as a novel therapeutic target." (PMID 39075554, 2024). "Compared with normal bladder samples, the protein expression of PLOD1, ATP6V1B1, HSD17B1, SERPINB7, and PYCR1 in bladder cancer tissues was upregulated, while EGR1 in cancer tissues was down-regulated." (PMID 37880682, 2023).
gastric cancer (2 papers, 2012 to 2017). A primary or metastatic malignant neoplasm involving the stomach. "The objective of the study was to investigate the role of genes (HSD3B1, CYP17A1, CYP19A1, HSD17B2, HSD17B1) involved in the steroid hormone biosynthesis pathway and progesterone receptor (PGR) in the etiology of gastric cancer in a population-based two-phase genetic association study." (PMID 23110082, 2012).
infertile (2 papers, 2019 to 2022). "In summary, similar trends of levels of the STAR/StAR, CYP19A1/aromatase, and HSD17B1/17β-HSD1 transcripts and proteins were observed in fertile and infertile patients from both groups." (PMID 31878927, 2019).
lysosomal storage disease (2 papers, 2017 to 2018). A metabolic disorder caused by mutations in proteins critical for lysosomal function, including lysosomal enzymes, lysosomal integral membrane proteins, and proteins involved in the post-translational modification and trafficking of lysosomal proteins. "In mice, a study reported that deleting the HSD17B1 gene results in a hypomorphic Naglu allele and a phenotype mimicking a lysosomal storage disease." (PMID 30257828, 2018).